MED7 (mediator complex subunit 7)
Description:
Component of the Mediator complex, a coactivator involved in the regulated transcription of nearly all RNA polymerase II-dependent genes. Mediator functions as a bridge to convey information from gene-specific regulatory proteins to the basal RNA polymerase II transcription machinery. Mediator is recruited to promoters by direct interactions with regulatory proteins and serves as a scaffold for the assembly of a functional preinitiation complex with RNA polymerase II and the general transcription factors.
Synonyms: ARC34; CRSP9; CRSP33
Tractability: Small molecule: a structure with a bound ligand is known. PROTAC: UniProt records ubiquitination sites on it; ubiquitination databases record sites on it; its protein half-life has been measured.
Gene: Protein-coding gene on chromosome 5 (157,137,424 to 157,159,019, reverse strand). Ensembl gene ENSG00000155868.
Subcellular location: Nucleus
Subcellular location (Human Protein Atlas): Nuclear bodies
Pathways (Reactome):
Gene expression (Transcription): Generic Transcription Pathway; MLL4 and MLL3 complexes regulate expression of PPARG target genes in adipogenesis and hepatic steatosis
Developmental Biology: Transcriptional regulation of white adipocyte differentiation
Disease: RSV-host interactions
Metabolism: PPARA activates gene expression
Gene Ontology:
Molecular function: protein binding; transcription coactivator activity; transcription coregulator activity; ubiquitin protein ligase activity
Biological process: regulation of transcription by RNA polymerase II; positive regulation of transcription elongation by RNA polymerase II; positive regulation of transcription initiation by RNA polymerase II; RNA polymerase II preinitiation complex assembly; transcription initiation at RNA polymerase II promoter; protein ubiquitination
Cellular component: core mediator complex; nuclear body; nucleus; transcription regulator complex; mediator complex; nucleoplasm; ubiquitin ligase complex
Genetic constraint (gnomAD): Loss-of-function variants: 7 observed, 17.28 expected, observed/expected ratio (o/e) 0.41, 90% interval 0.23 to 0.76. The upper end of that interval is the gene's LOEUF score, 0.76, which puts it in group 3 of 6, group 1 being the genes least tolerant of losing a copy. Missense variants: 239 observed, 300.68 expected, observed/expected ratio (o/e) 0.79, 90% interval 0.71 to 0.88. Synonymous variants: 85 observed, 95.08 expected, observed/expected ratio (o/e) 0.89, 90% interval 0.75 to 1.07.
Homologues: Orthologues: chimpanzee MED7 (100% identical), dog MED7 (99% identical), macaque MED7 (99% identical), guinea pig MED7 (99% identical), pig MED7 (98% identical), rat Med7 (98% identical), mouse Med7 (97% identical), tropical clawed frog med7 (80% identical), zebrafish med7 (78% identical), Caenorhabditis elegans T13C5.10 (6% identical), Caenorhabditis elegans T13C5.2 (6% identical), Caenorhabditis elegans T25B2.3 (6% identical), and 6 more. Paralogues in human: HAVCR2 (14% identical), TIMD4 (14% identical), HAVCR1 (12% identical).
Diseases named in the same sentence as MED7 in open-access papers:
MED7 is named in the same sentence as 10 diseases in open-access papers, as found by Europe PMC text mining. Sharing a sentence is not in itself a finding about the gene and the disease. The quoted sentences say what the papers report.
breast carcinoma (3 papers, 2018 to 2022). "With respect to other tumors, MED7 underexpression was correlated with an increased risk of gastrointestinal stroma, while in breast cancer, especially ER + luminal subtypes, MED7 was positively correlated with improved prognosis." (PMID 36330335, 2022). "Thus MED7 expression was assessed in large breast cancer (BC) cohorts to determine clinicopathological significance." (PMID 29588513, 2018).
Cognitive impairment (1 paper, 2024). Abnormal cognition is characterized by deficits in thinking, reasoning, or remembering. "MED7 is a coactivator involved in the regulation of the transcription of nearly all RNA-polymerase-II-dependent genes, which was connected to folate-dependent cognitive impairment." (PMID 38474143, 2024).
testicular cancer (1 paper, 2016). A primary or metastatic malignant neoplasm that affects the testis. "In testicular cancer only a single overexpression (MED15) was found; while other subunits were underexpressed (MED17, MED7, MED10, MED1)." (PMID 27050271, 2016).
tumours (3 papers, 2018 to 2022). "High expression of both MED7 mRNA and protein were significantly associated with better behaving tumour characteristics, viz., low histological grade, older age, good NPI, ER+/PR+ tumours and histological subtypes of good prognosis." (PMID 29588513, 2018). "High MED7 mRNA and protein expression was associated with good prognostic factors: low grade, smaller tumour size, good NPI, positive hormone receptor status (p < 0.001), and negative LVI (p = 0.04) status." (PMID 29588513, 2018). "High nuclear MED7 expression was associated with smaller tumour size (p < 0.0001), lower grade (p < 0.0001), lower mitotic scores (p < 0.0001), higher tubule formation (p = 0.0004) and less nuclear pleomorphism (p < 0.0001)." (PMID 29588513, 2018). "MED7’s positive association with luminal markers indicate its role in better behaving tumours." (PMID 29588513, 2018). "Overexpression of MED7 particularly appears to play a significant role in ER+luminal subtype of BC, and given its association with multiple ER-related markers, further functional assessment is necessary to reveal the specific role played by this Mediator protein in these ER-positive tumours." (PMID 29588513, 2018). "Subsequently, we constructed a risk model based on four LMAGs—LCAT, MED22, MED7, and TXNRD1—which presented noteworthy prognostic values and was closely associated with tumor grade, tumor stage, and T-staging." (PMID 36330335, 2022). "In ER-negative tumours, only MED7 (p < 0.00001), BEX1 (p = 0.032) and N-cadherin (p = 0.034) showed significant association with RXRG." (PMID 31558802, 2019). "On one hand, it is known that EGFR overexpression in BC is associated with increased tumour size and worse patient outcomes and negatively correlates with ER status, explaining the observed negative association with MED7." (PMID 29588513, 2018). "The biomarkers characterised on the Nottingham Primary series also serve as indicators of possible molecular networks in ER+ tumours where MED7 may be an interacting partner." (PMID 29588513, 2018). "Also, the overall correlation with good prognosis in the whole cohort seems to stem chiefly from MED7’s strong prognostic correlations in ER+Luminal A tumours." (PMID 29588513, 2018). "Some ER-positive tumours are known to recur in the long run; as MED7 is of prognostic significance over a long time span, this may help discriminate between good vs poorly performing ER-positive tumours." (PMID 29588513, 2018). "When comparing the levels of MED7 mRNA expression in the intrinsic (PAM50) subtypes, significant correlations were observed with luminal subtype tumours while the basal subtype showed the least expression levels (p < 0.0001)." (PMID 29588513, 2018). "Though the prognostic effect of MED7 is not observed in ER− tumours, the prognostic value in ER-positive BCs is potentially useful." (PMID 29588513, 2018).
carcinoma (1 paper, 2018). A malignant tumor arising from epithelial cells. "Lobular carcinomas showed significantly higher expression of MED7 (p = 0.001) in comparison to ductal no special type and medullary subtypes." (PMID 29588513, 2018).
infection (1 paper, 2020). The state of being infected such as from the introduction of a foreign agent such as serum, vaccine, antigenic substance or organism. "Unexpectedly, distinct subunits appear to be involved in the response to this type of infection, in which the pathogen breaks through the cuticle, namely Med27 and possibly Med7 and Med29." (PMID 33746938, 2020).
MED7 also shares sentences with these, for which no sentence is quoted: Fibroadenoma (1 paper); gastrointestinal stromal tumours (1); invasive lobular carcinoma (1); lobular carcinomas (1).